CDCA5 (cell division cycle associated 5)
Diseases named in the same sentence as CDCA5 in open-access papers (continued):
Sharing a sentence is not in itself a finding about the gene and the disease.
cancer (continued). "Subsequently, the expressions of CDCA2, CDCA3, CDCA4, CDCA5, CDCA7, and CDCA8 genes in COAD samples across various cancer stages were verified using the GEPIA2 database." (PMID 39924497, 2025). "Our study revealed a strong connection between CDCA5 and the immune gene CD276 in various cancer types." (PMID 38213717, 2024). "The results show that the expression of CDCA5 in TNBC is increased, which plays an important role in the proliferation and migration of cancer cells." (PMID 35726220, 2022). "By retrieving related literature, we found that CDCA5 and CDCA8, as important regulatory proteins in the cell cycle in cancer, were recognized as oncogenes." (PMID 33449451, 2021). "Among them, seven genes of CDCAs (CDCA1/NUF2: P = 2.73E-22, CDCA2: P = 1.52E-16, CDCA3: p = 1.50E-20, CDCA5: P = 1.77E-20, CDCA6/CBX2: P = 6.87E-19, CDCA7: P = 5.92E-16, and CDCA8: P = 1.67E-18) were all up-regulated in 19 cancer datasets." (PMID 33665158, 2020). "Gene expression analysis of CDCA5 reveals that CDCA5 promoter methylation levels, mRNA and protein expression levels were consistent in KIRC, COAD, HNSC, LUAD, and UCEC, and high CDCA5 expression was related with the development of cancer." (PMID 38213717, 2024). "However, studies suggested that the expression of CDCA5 in cancer cells of TNBC patients is significantly higher than that of normal breast cells, and patients with high expression of CDCA5 have poor prognosis." (PMID 35726220, 2022). "MCF10A cells were routinely cultured as the negative control group to analyze the effect of CDCA5 expression on the proliferation and migration of cancer cells." (PMID 35726220, 2022). "In summary, shRNA interference technology will be used to affect the expression of CDCA5, explore the effect of CDCA5 expression on the proliferation and metastasis of TNBC cancer cells, and find new potential targets for the subsequent clinical treatment of TNBC." (PMID 35726220, 2022). "Additionally, the absence of significant differences in the mRNA expression levels of CDCA2, CDCA3, CDCA4, CDCA5, CDCA7, and CDCA8 across different cancer stages of COAD suggests that these genes may play a consistent role throughout the progression of COAD." (PMID 39924497, 2025).
infection (2 papers, 2020 to 2023). The state of being infected such as from the introduction of a foreign agent such as serum, vaccine, antigenic substance or organism. "On the other hand, cohesion of sister chromatids is a dynamic process regulated by genes such as Cdca5, Cdca8(Borealin), Plk1, Sgo1, and Sgo2a, which were up-regulated late in infection." (PMID 38107402, 2023). "Additionally, UMUC3, which exhibited lower CDCA5 expression, was transfected with the OE-CDCA5 lentivirus, and its infection efficiency was also confirmed." (PMID 32201512, 2020).
CDCA5 also shares sentences with these, for which no sentence is quoted: acute myeloid leukemia (1 paper); diffuse large B-cell lymphoma (1); digestive system cancer (1); esophageal cancer (1); Ewing sarcoma (1); head and neck squamous cell carcinoma (1); Hepatitis (1); invasive ductal breast carcinoma (1); lymphoid neoplasm (1); melanoma (1); myeloid malignancies (1); osteosarcoma (1); ovarian serous cystadenocarcinoma (1); pancreatic adenocarcinoma (1); pancreatic cancer (1); pleural mesothelioma (1); renal clear cell carcinoma (1); sarcoma (1); Skin cutaneous melanoma (1); thymoma (1); thyroid carcinomas (1); urothelial cell carcinoma (1); uterine carcinosarcoma (1).